CD4 (CD4 molecule)
Diseases named in the same sentence as CD4 in open-access papers (continued):
Sharing a sentence is not in itself a finding about the gene and the disease.
Opportunistic infection (continued). "This puts people co infected at a risk of opportunistic infections, since the CD4+ cells play an important role in the immune system, especially the adaptive immune system." (PMID 35222562, 2021). "HIV was the immune system and acceleration viral replication responsible depletion of CD4 count and associated with precipitation of new episode for opportunistic infections." (PMID 34812290, 2021). "Idiopathic CD4 T-lymphocytopenia (ICL) is a rare entity that is associated with decreased immunity which predisposes affected individuals to opportunistic infections and malignancies." (PMID 34938625, 2021). "Factors such as history of STI, hospital admission, provision of traditional delivery care, family history of HBV, unsafe sex, viral load, CD4 count, opportunistic infections, and presence of anemia were statistically associated with HBV infection." (PMID 33930097, 2021). "Next to the decreases in the number of CD4+ cells which leads to opportunistic infections, HIV-related immune activation is associated with several prevalent comorbidities in the HIV-positive population such as cardiovascular and bone disease." (PMID 33643320, 2021). "HIV patients with low CD4 count, generally less than 200 cells/μL, are at risk of developing opportunistic infections." (PMID 34650858, 2021). "Antiretroviral therapy is key in reversing the HIV-induced immunosuppression, with an associated increase in CD4 counts that prevents and even treats opportunistic infections." (PMID 34214127, 2021). "Severe lymphopenia, unresponsiveness to in vivo and in vitro tests, and marked decrease of CD4+ cells were reported in HIV infected patients in association with opportunistic infection." (PMID 34591866, 2021). "We also suggest that more attention should be given to patients in critical condition due to low CD4+ T cell counts and increased risk of opportunistic infections and lower antiviral immune surveillance." (PMID 34626490, 2021). "Lower CD4 count made HIV patients more vulnerable to suffer from opportunistic infections and increased the risk of kidney injury." (PMID 32160882, 2020). "Specifically, lower CD4 count has strong correlation with sever immune depletion, hence risk of opportunistic infections." (PMID 32527231, 2020). "With regard to recipients of a renal transplantation low numbers of CD4+ T cells are associated with cardiovascular mortality and opportunistic infection with Pneumocystis jiroveci pneumonia after transplantation." (PMID 32082402, 2020). "Lessons from HIV infection indicated that a low CD4+ T-cell counts increases the risk of opportunistic infections and lower antiviral immune surveillance, suggesting more attention should to be given to patients in critical condition." (PMID 32641700, 2020). "Theoretically, this would put untreated HIV-infected patients with low CD4 cell numbers at particularly high risk of superimposed opportunistic infections during COVID-19." (PMID 32574323, 2020). "It is known that viral replication has an inverse relationship with CD4 count, and lower CD4 count increases the risk and occurrence of opportunistic infections and high an attrition rate." (PMID 32611405, 2020). "A low CD4+ cell count, a high antigen load from an opportunistic infection, and a short interval between the treatment of an opportunistic infection and the initiation of HAART are also risk factors associated in the development of IRIS." (PMID 32631361, 2020). "Low CD4+ T-cell counts lead to increased risk for opportunistic infections, and M. tb is often one of the first severe opportunistic infections acquired." (PMID 32824563, 2020). "Ultimately, these processes disrupt CD4 T cell homeostasis and reduce the levels of critical effector/memory T cells below the threshold necessary to prevent opportunistic infections or associated pathologies." (PMID 33643305, 2020).
Opportunistic infection (continued). "Of note, bendamustine is associated with a reduction in CD4 lymphocyte counts and an increased risk of opportunistic infections." (PMID 32183871, 2020). "The CD4 counts decreased, the viral load rose, and he was more susceptible to opportunistic infections." (PMID 32604973, 2020). "The main opportunistic infections were associated with an increased risk of death after adjusting for CD4 count, age, period, and antiretroviral treatment." (PMID 32276647, 2020). "Viral load testing is being scaled up replacing CD4 monitoring, yet absolute CD4 cell counts provide the risk stratification to target evaluation for opportunistic infections, including CrAg screening." (PMID 31679007, 2020). "HIV infection induces a gradual depletion of CD4 T cells, leading to decline of host immunity which increases the risk of opportunistic infections and elevates mortality." (PMID 33643305, 2020). "The blood CD4+ T-cell counts of the HZ patients were mostly above the levels predisposing to opportunistic infections, with a median near 400 cells/μL in the treated groups and 350 cells/μL in the discordant group off ART." (PMID 32697807, 2020). "Antiretroviral therapy (ART) inhibits HIV viral replication, reconstitutes CD4 T-cell counts and immunity, thereby decreasing the risk for opportunistic infections such as Kaposi’s sarcoma, candidiasis and tuberculosis." (PMID 33007050, 2020). "Nevertheless CD4 remains the best measurement of a patient's immune and clinical status, risk of opportunistic infections, and it is being used to support diagnostic decision-making, particularly for patients with advanced HIV disease." (PMID 30673713, 2019). "It is recommended that both viral load monitoring and CD4 cell count monitoring be used since viral load determines the need for treatment change and CD4 cell count helps in monitoring the risk of opportunistic infection (OI) and treatment failure." (PMID 30770728, 2019). "Good adherence to ART has revolutionized HIV medicine as it leads to suppressed viral load and repopulation of diminished CD4 T-lymphocytes and the resultant decreases mortality as well as risk of opportunistic infection." (PMID 31692880, 2019). "The gradual decrease in CD4 T lymphocytes cells (below 200 cells/μL) ultimately results in a loss of control over immune response and the development of various opportunistic infections." (PMID 31690039, 2019). "Treatment in an HIV infected especially children results in a reduced risk of opportunistic infection as well as improved CD4 count." (PMID 31781388, 2019). "In practice, most programmes rely upon CD4+ cell count to make determinations about risk of opportunistic infections." (PMID 31274541, 2019). "In these patients, the presence of such immune alterations other than CD4 lymphopenia is associated with a higher risk of severe opportunistic infections and a greater mortality." (PMID 31781092, 2019). "Children with CD4 counts or percentages below the threshold are at higher risk of developing opportunistic infections, which escalates the possibility of death during the early phase of treatment prior to responding to HAART drugs." (PMID 29482600, 2018). "It is strongly recommended that HIV-positive women should have a CD4+ count of 200 cells/mL or more before considering pregnancy so that their risk of opportunistic infections and deteriorating health during the pregnancy can be minimised." (PMID 30473876, 2018). "HIV causes progressive depletion of the CD4+ T cells, leading to life-threatening opportunistic infections during the natural course of the disease." (PMID 30344850, 2018). "An impaired immune system, as seen in patients with low CD4 counts, causes these patients to be susceptible to opportunistic infections like DH." (PMID 29276711, 2017). "The clinical consequences of being an INR are dire, because the severe CD4+ lymphopenia increases dramatically the risk of developing opportunistic infections and malignant disease." (PMID 29093707, 2017).
Opportunistic infection (continued). "It is widely accepted by the scientific community that the risk of onset of opportunistic infection increases considerably as the CD4+ falls below 350 cells/mm3, even if the primary prophylaxis starts at 200 cells/mm3." (PMID 28166729, 2017). "With time the body fails to contain the viral replication and immune deficiency sets in, being marked by low CD4 counts with increased morbidity and mortality from opportunistic infections." (PMID 28595630, 2017). "The main direct and indirect consequence of the virus activity was infected and uninfected CD4 + T cells (CD4) death, causing progressively worsening immunosuppression, which exposed patients to the growing risk of opportunistic infection and death." (PMID 27462361, 2016). "HIV infection depletes the CD4 cell counts with its attendant’s susceptibility to opportunistic infections of which TB is common." (PMID 27232185, 2016). "The Swiss HIV Cohort study reported that the risk of developing opportunistic infections is increased by 2.5 if the CD4 count is between 51–200 cells/mm; this risk increases to 5.8 for counts <50 cells/mm." (PMID 27405321, 2016). "Various studies have demonstrated that lower CD4 counts are associated with an increased prevalence of opportunistic infections." (PMID 27405321, 2016). "Viral hepatitis (HBV and/or HCV), opportunistic infections, being male, and current CD4 count <200 cells/mm3 were significantly associated with elevated liver enzymes." (PMID 27493798, 2016). "Not being on ART is a known risk factor for the development of opportunistic infections even at high CD4 counts." (PMID 27286814, 2016). "Being malnourished, late WHO stage, having low CD4 cell count, ambulatory and bedridden functional status and two and more opportunistic infections were factors independently associated with death." (PMID 27998310, 2016). "Reductions in CD4+ cells and the resulting inflammation and immunosuppression are associated with onset of multiple co-morbid opportunistic infections such as tuberculosis, candidiasis, pneumonia, Kaposi’s sarcoma, and other conditions." (PMID 27716818, 2016). "Studies have substantiated the fact that low CD4 cell count, a marker of advanced immunodeficiency, was associated with opportunistic infection thereby increasing the likelihood of death." (PMID 27998310, 2016). "CD4 T cells play an important role in the occurrence of opportunistic infections in HIV infected patients and the risk of opportunistic infection is especially high when CD4 T cell count is <100 cells/mm3." (PMID 26871791, 2016). "PLWHA with low CD4 + T cells count are more susceptible to opportunistic infections associated with the presence of gastrointestinal symptoms, either in the upper and lower gastrointestinal tract." (PMID 27749931, 2016). "Lower CD4 count is associated with an increased risk of opportunistic infection and increase risk of malignancy." (PMID 27405321, 2016). "Treatment of HIV-infected patients with highly active antiretroviral therapy (ART) leads to immune reconstitution as shown by increases in CD4 lymphocyte counts, decreased risk of opportunistic infections and improved survival." (PMID 27688793, 2016). "The CD4 count, which is routinely used to determine the risk of opportunistic infection, is typically included in trials of HIV therapeutic vaccines." (PMID 26561337, 2015). "This can be attributed to the well establishment that CD4+ T lymphocyte cells <200 cells/μl is associated with a higher risk of opportunistic infection and poor disease progression." (PMID 25857950, 2015). "Future measurements will include an analysis of LTFU risk factors, late diagnosis, and incidence of opportunistic infections by CD4 cell counts." (PMID 26425365, 2015). "It is thought that the susceptibility of HIV+ individuals to C. neoformans infection is primarily due to the depletion of CD4 T cells, which leads to defects in both innate and adaptive immunity that predispose to opportunistic infections." (PMID 26252005, 2015).
Opportunistic infection (continued). "These factors include depression, age, sex, religion, level of education, CD4 count, marital status, opportunistic infections and socio-economic status were found to be associated with or to affect QoL [8,10,11,13 276,14,15,16]." (PMID 26039733, 2015). "Though numerous studies have evaluated peripheral CD4+ T cell counts and associated them with onset of opportunistic infections, few studies have examined the dynamics of CD4+ T cells in oral mucosa during HIV infection and HAART." (PMID 26065003, 2015). "We wanted to examine the efficacy of nutritional supplements as adjunct to HAART, given the high mortality and risk of opportunistic infections in the first several months of antiretroviral therapy particularly in those with low CD4 T cell counts." (PMID 26285704, 2015). "Among PLHIV, food insecurity is associated with incomplete HIV-1 RNA suppression, CD4 decline, increased opportunistic infections, hospitalizations, and HIV-related mortality." (PMID 25937825, 2015). "Opportunistic infection and CD4 cell count were associated with prevalence of anemia before HAART initiation." (PMID 25335859, 2014). "Late onset combined immunodeficiency (LOCID) is a recently described variant of common variable immunodeficiency (CVID), involving adult patients presenting with opportunistic infections and/or low CD4+ lymphocyte counts." (PMID 24799913, 2014). "The progressive loss of CD4+ clones puts the patient at increasing risk of opportunistic infections." (PMID 25089078, 2014). "Delay in initiating antiretrovirals exposes the patient to a high risk of another opportunistic infection, especially if the CD4 count is <50/mm3." (PMID 24942364, 2014). "For example, CD4+ T-cell counts based on patient age (for example, a Z-score) better predict opportunistic infection risk in HIV-positive children than absolute CD4 counts." (PMID 25029487, 2014). "There was a significant association between prevalence of anemia with CD4 cell count and opportunistic infections before HAART initiation." (PMID 25335859, 2014). "As HIV disease continues and the number of CD4+ T-lymphocytes continues to decrease, the patient is at higher risk for the development of opportunistic infections, such as CMV retinitis." (PMID 25089078, 2014). "CD4 has been used as a marker of immunocompetence in HIV infected patients, with higher CD4 counts indicating better immune response in these patients to opportunistic infections and other pathogenic infections." (PMID 25225572, 2014). "Our findings imply that despite sustained viral suppression, the persistently low CD4 T-cell function is likely to predispose suboptimal responders to opportunistic infections and severe Staphylococcus aureus infections." (PMID 23786370, 2013). "For instance, although the SWV programme paid the initial consultation fee and for CD4 count test, other charges are associated with treatment, women had to bear other costs such a US$ 10 fee for consulting a doctor for management of opportunistic infections." (PMID 23898942, 2013). "Despite high ART coverage in this setting, a large fraction of the population have low CD4 cell counts that put them at increased risk of opportunistic infections like TB." (PMID 23894603, 2013). "Lower bodyweight is a proxy indicator of advanced disease (low CD4 and worst clinical stage) and risk factor of opportunistic infections like TB." (PMID 24369908, 2013). "Our patient's antiretroviral naiveté, CD4 count <50, and active opportunistic infection at the time of initiation of HAART were risk factors for the development of IRIS." (PMID 24151569, 2013). "The lower the CD4 count of the study population the more predisposed to opportunistic infections of the lung and the more the tendency for the chest radiograph findings to be atypical." (PMID 23077699, 2012).
Opportunistic infection (continued). "Feline immunodeficiency virus (FIV) causes an immune system disease in domestic cats (Felis catus) involving depletion of the CD4+ population of T lymphocytes, increased susceptibility to opportunistic infections, and sometimes death." (PMID 22590677, 2012). "The selective loss of intestinal CD4+ T cells is likely to explain, together with mucosal barrier breakdown, the preponderance of opportunistic infections at mucosal sites." (PMID 21858117, 2011). "In HIV infection, CD4 cell number progressively decreases, predisposing affected individuals to the development of opportunistic infections or malignancies if they are left untreated." (PMID 20687947, 2010). "Effective antiretroviral therapy reduces HIV-1 RNA levels, improves CD4 counts, and lowers the risk of opportunistic infections and malignancies." (PMID 20687947, 2010). "The onset of opportunistic infections in HIV-positive patients is generally associated with a low CD4 count." (PMID 23346337, 2010). "Effective antiretroviral therapy reduces HIV-1 RNA levels, improves CD4 T-cell counts, and lowers the risk of opportunistic infections and malignancies." (PMID 20687947, 2010). "It has long been recognized that CD4 counts below 200 cells/ml expose HIV-infected patients to a very high risk for opportunistic infections and death, the main reason why therapy is started when CD4 count drops below that level." (PMID 19558677, 2009). "These defects have been found to be more pronounced in individuals with higher viremia and/or lower CD4+ T cell counts and to be associated with the development of opportunistic infections and tumors." (PMID 19936055, 2009). "Delayed ART initiation also impacts negatively immunological recovery following ART initiation, as patients with a low CD4 lymphocyte nadir have a slower increases in CD4 count, prolonging the period at risk of opportunistic infections." (PMID 18325119, 2008). "Using the CD4 threshold criteria, we found that 43%, 42% and 19% had SO-CD4 at 6, 12 and 24 months respectively; thereby remaining at risk of opportunistic infections." (PMID 18957083, 2008). "People with advanced HIV who receive highly active antiretroviral treatment (HAART) tend to have increases in their CD4+ cell counts and lose their susceptibility to these so-called opportunistic infections and cancers." (PMID 17388662, 2007). "However, our control population consisted of clinically relevant persons with advanced HIV disease (CD4 <200 cells/mL) and other opportunistic infections, which are representative of the population at risk for talaromycosis." (PMID 40562724, 2025). "Patients who achieve a CD4+ count above key thresholds (e.g., surpassing 200 cells/μL is associated with the highest risk for opportunistic infections, and ideally >500 cells/μL indicates approaching the lower limit of normal) are considered to have a favorable immune recovery." (PMID 40868140, 2025). "A decreased CD4 lymphocyte count may also have prognostic significance and is associated with an increased risk of opportunistic infections." (PMID 41465777, 2025). "Indeed, bendamustine is consistently associated with prolonged lymphopenia, especially CD4 + depletion, delayed immune recovery (median 7–9 months), and a higher incidence of opportunistic infections (PJP, VZV, CMV)." (PMID 41175237, 2025). "With CD4+ counts negatively impacted by alcohol, the risk of opportunistic infections is increased." (PMID 41295583, 2025). "The difference in median CD4 count (10 cells/mm3 for cases vs 19 cells/mm3 for controls) is not clinically significant since both are considered severely immunocompromised with the same risk of opportunistic infections." (PMID 40749024, 2025).